SST (somatostatin)
Diseases named in the same sentence as SST in open-access papers (continued):
Sharing a sentence is not in itself a finding about the gene and the disease.
Stroke (2 papers, 2021 to 2025). Sudden impairment of blood flow to a part of the brain due to occlusion or rupture of an artery to the brain. "Specifically, in the striatum the number of these neurons is usually reduced shortly after stroke (4 h/1 day) followed by normalization to baseline-like values in 3/7 days, likely due to down- and up-regulation of somatostatin expression." (PMID 32447613, 2021). "Apart from PV+ interneurons, other interneurons could be involved in stroke recovery and among them, somatostatin+ (SOM+) neurons are plausible candidates." (PMID 32447613, 2021). "We found that rehabilitation significantly increased synaptic input from PV interneurons to stroke-projecting neurons, but not from the other major classes of inhibitory neurons: somatostatin, or 5HT3a interneurons." (PMID 40089466, 2025).
TSHomas (2 papers, 2022 to 2025). "Somatostatin and dopamine receptors can be expressed in both TSHomas and GHomas, especially in mixed pituitary TSH/GH adenoma cells." (PMID 36619586, 2022). "It has also been shown that TSHomas that respond poorly to SSA have a lower SST5/SST2 and SST/DR2 expression ratio and respond better to DA." (PMID 40259920, 2025).
vascular dementia (2 papers, 2020 to 2022). A degenerative vascular disorder affecting the brain. "A previous study on the SST gene revealed that the content of somatostatin in the cerebrospinal fluid of patients with vascular dementia was significantly lower than in a healthy person." (PMID 36213445, 2022).
absence seizures (1 paper, 2020). "Moreover, somatostatin-positive interneurons in the somatosensory cortex are active during quiet wakefulness, the brain state where most absence seizures are expressed (Halász, 2015) and their silencing increases burst firing in cortical pyramidal neurons." (PMID 32437558, 2020).
acute coronary syndrome (1 paper, 2023). Signs and symptoms related to acute ischemia of the myocardium secondary to coronary artery disease. "The current study adds to the expanding evidence base that vitamin D supplementation in patients with acute coronary syndromes improves echocardiographic parameters by lowering markers of cardiac fibrosis such as pro-inflammatory cytokine (PINK)-1 and soluble somatostatin (soluble ST2)." (PMID 37259407, 2023).
amblyopia (1 paper, 2022). Decreased vision that results from abnormal visual development. "Specifically, amblyopia has been linked to increased numbers of active somatostatin positive interneurons, without any detectable effect on either vasointestinal protein or parvalbumin positive cells." (PMID 35558878, 2022).
anal carcinoma (1 paper, 2021). "A cross‐sectional series of 176 tissue samples of anal cancer, AIN3, AIN2, AIN1 and control biopsies obtained in HIV‐negative women and men was tested for six methylation markers (ASCL1, LHX8, SST, WDR17, ZIC1 and ZNF582)." (PMID 33580586, 2021).
autonomic diabetic neuropathy (1 paper, 2024). "These may include the lack of trophic action of insulin, glucagon, and somatostatin, autoimmune damage to the pancreas, and the presence of autonomic diabetic neuropathy, which can impair the entero-pancreatic reflex." (PMID 38398492, 2024).
benign prostate hyperplasia (1 paper, 2022). "Benign conditions such as benign prostate hyperplasia have similarly been shown to have upregulated somatostatin and are [68Ga]Ga-DOTATATE PET positive." (PMID 36551525, 2022).
bladder tumor (1 paper, 2021). "Methylation levels of GHSR, SST, and ZIC1 were determined using paired bladder tumor tissues and cervical scrapes as a reference." (PMID 33572525, 2021). "Methylation levels of the markers GHSR, SST, and ZIC1 were determined in bladder tumor tissues, in both paired natural voided urine and nephrostomy urine." (PMID 33572525, 2021).
brain infarct (1 paper, 2021). "Accordingly, SST and a related peptide, cortistatin-14, and the synthetic SSTR2, SSTR3, and SSTR5 agonist octreotide significantly reduce brain infarct size in a middle cerebral artery occlusion model." (PMID 34803662, 2021).
central sleep apnea (1 paper, 2025). "This study aimed to discriminate central sleep apnea and obstructive sleep apnea in CDKL5‐knockout mice, and explore changes in the somatostatin neurons expressing high levels of neurokinin‐1 receptors within the preBötzinger complex." (PMID 39049436, 2025).
Chylothorax (1 paper, 2021). The presence of chyle in the thoracic cavity. "In human milk somatostatin is found in high concentrations, thus contributing a direct beneficial effect toward reducing lymph production when human milk is continued in infants with chylothorax." (PMID 34446079, 2021).
Cluster headache (1 paper, 2018). A type of headache characterized by repeated attacks of unilateral pain lasting 15 to 180 minutes and associated with local autonomic signs. "A multicenter, placebo-controlled, single-dose study is underway to assess the safety and effectiveness of pasireotide (SOM230), a long-acting release somatostatin analogue, in acute cluster headache treatment (NCT02619617)." (PMID 29516437, 2018). "In cluster headache patients, it has been shown that they have lower levels of plasma somatostatin during both attacks and attack-free periods, when compared to normal healthy individuals." (PMID 29516437, 2018).
colorectal adenocarcinoma (1 paper, 2015). The most common type of colorectal carcinoma. "Furthermore, we tested the methylation status of SST in biopsy samples, and the cell growth inhibitory effect of the SST analogue octreotide in human colorectal adenocarcinoma cell line." (PMID 25723531, 2015). "Since treatment with the somatostatin analogue octreotide resulted in reduced cell proliferation and elevated apoptosis in a human colorectal adenocarcinoma cell line, our results suggested that the lack of local SST production may contribute to elevated and uncontrolled cell proliferation in CRC." (PMID 25723531, 2015).
Cough (1 paper, 2025). A sudden, audible expulsion of air from the lungs through a partially closed glottis, preceded by inhalation. "In a mouse cough model, selective activation of somatostatin (SST+) neurons innervating the trachea using Ly344864 and IL-31 significantly increased the frequency of coughing compared to the control group." (PMID 40415887, 2025).
cryptosporidiosis (1 paper, 2018). Intestinal infection with organisms of the genus Cryptosporidium. "The development of intestinal cryptosporidiosis in this rat model and the increased somatostatin mRNA levels suggest an immunomodulatory role for SSTRs in the rat jejunum under normal and infectious conditions." (PMID 29522573, 2018).
cysticercosis (1 paper, 2014). "In the current studies, we addressed the role of somatostatin in granulomatous inflammation associated with cysticercosis using a murine model of Taenia crassiceps infection." (PMID 25530957, 2014). "To examine the contribution of somatostatin to granuloma formation in cysticercosis, we determined the number and size of granulomas within the peritoneal cavity of T. crassiceps-infected WT mice and SOM−/− mice." (PMID 25530957, 2014). "Our finding that somatostatin downmodulates inflammatory responses suggests the possibility of using somatostatin analogues, instead of corticosteroids, as an immunomodulator in these patients to downmodulate granulomatous inflammation in neurocysticercosis." (PMID 25530957, 2014). "To examine the contribution of somatostatin to parasite burden in cysticercosis, we infected WT mice and somatostatin knockout (SOM−/−) mice intraperitoneally with 10 cysts of the ORF strain of T. crassiceps, as described." (PMID 25530957, 2014). "We hypothesized that the somatostatin is one of the factors that downmodulates granulomatous inflammation and that, by doing so, it negatively regulates parasite burden in murine cysticercosis." (PMID 25530957, 2014). "In the current studies, we used somatostatin knockout (SOM−/−) mice to examine the hypothesis that SOM downmodulates granulomatous inflammation in cysticercosis, thereby promoting parasite growth." (PMID 25530957, 2014).
demyelinating disease (1 paper, 2021). A broad group of disorders that affect the myelin sheaths that cover the neurons. "In these top 10 proteins, IGF2, IGBP7 and SST were the proteins with large fold changes (FC=4.43, 2.60 and 0.17).Besides, we found that IGF2, IGFBP7 and SST are related to demyelinating disease in previous research." (PMID 34489947, 2021).
fibromyalgia (1 paper, 2023). A chronic disorder of unknown etiology characterized by pain, stiffness, and tenderness in the muscles of neck, shoulders, back, hips, arms, and legs. "Increased somatostatin tone has been observed in fibromyalgia and modulates the stress-induced suppression of pituitary hGH release." (PMID 36998474, 2023).
gallbladder carcinoma (1 paper, 2007). "Pre-treatment of a gallbladder carcinoma cell line with somatostatin increased sensitivity to doxorubicin, as evidenced by inhibition of cancer cell growth both in vitro and in vivo." (PMID 17617924, 2007). "In the current study, we evaluated the effect of doxorubicin on the chemosensitivity of gallbladder cancer cells and xenograft growth after treatment with somatostatin." (PMID 17617924, 2007). "This is confirmed by our results as we demonstrated that SST significantly inhibits cell growth in a gallbladder cancer cell line in a concentration-dependent manner." (PMID 17617924, 2007). "In the current study, the effect of SST on the regulation of growth and cell cycle of gallbladder cancer cells was investigated." (PMID 17617924, 2007). "Twenty-four hours after somatostatin treatment, doxorubicin was gradually added and the growth curve of gallbladder cancer cells was determined." (PMID 17617924, 2007). "The hastened cell growth inhibition was significant and confirmed by the calculation of the IC50 values which were 15.00 μg/ml DOX upon treatment of the gallbladder cancer cell line with only DOX and 4.50 μg/ml upon co-treatment with DOX and SST (P < 0.01)." (PMID 17617924, 2007).
gastric carcinoid tumors (1 paper, 2016). "A very recent paper has also demonstrated reduced p27 expression in gastric carcinoid tumors arising in transgenic mice that was hypergastrinemic as a result of deletion of Men1 and somatostatin along with treatment with omeprazole." (PMID 27323780, 2016).
gastric disease (1 paper, 2021). "However, a surprisingly high positive percentage was found in the tNGS study for DM2 in familial patients (50%), which suggests a correlation with an achlorhydria-mediated gastric disease and might be explained by achlorhydria-mediated SST-deregulation." (PMID 34944008, 2021).
Gastrointestinal angiodysplasia (1 paper, 2022). Dysplasia affecting the vasculature of the gastrointestinal tract. "SST, which encoded somatostatin, is an important hormone to maintain homeostasis of intestine function, and relative analogs also can be used as therapeutic agents for gastrointestinal angiodysplasias." (PMID 36008975, 2022).
goblet cell carcinoid (1 paper, 2008). "Based on our results we find out that apart from the described serotonin-, somatostatin- and chromogranin A-positive endocrine cells, the goblet cell carcinoid contains also synaptophysin-positive endocrine cells." (PMID 18252007, 2008).
Hepatic cysts (1 paper, 2012). "Recent studies have shown that somatostatin and mTOR inhibitors may have benefit hepatic cyst." (PMID 23304619, 2012).
holoprosencephaly (1 paper, 2016). Holoprosencephaly (HPE) is a complex brain malformation resulting from incomplete cleavage of the prosencephalon, occurring between the 18th and 28th day of gestation, and affecting both the forebrain and face, which results in neurological manifestations and facial anomalies of variable severity. "Interestingly, in cases of human holoprosencephaly (HPE) with severe ventral forebrain hypoplasia, it was reported that only subpopulations of cortical interneurons (namely, those which express either NOS1, NPY, or SST) were absent, while calretinin-positive interneurons were still detected." (PMID 27069486, 2016).
hyperinsulinemic hypoglycemia (1 paper, 2024). An inherited autosomal recessive syndrome characterized by the disorganized formation of new islets in the pancreas and congenital hyperinsulinism. "Additionally, somatostatin analogs help prevent hyperinsulinemic hypoglycemia during malaria complications." (PMID 39492784, 2024).
hyperparathyroidism (1 paper, 2019). Hyperfunction of the parathyroid glands resulting in the overproduction of parathyroid hormone. "Furthermore, somatostatin analogs have been tested in the treatment of hyperparathyroidism alongside surgery without an apparent effect on the patients’ serum calcium or PTH levels." (PMID 31336364, 2019).
Hypervolemia (1 paper, 2022). An increase in the amount of intravascular fluid, particularly in the volume of the circulating blood. "This includes the use of NSBBs and somatostatin analogs, which help decrease the hyperdynamic circulation, as well as diuretics to decrease hypervolemia and antibiotics to lower ammonia-producing gut bacteria." (PMID 36300180, 2022).
Impaired glucose tolerance (1 paper, 2018). An abnormal resistance to glucose, i.e., a reduction in the ability to maintain glucose levels in the blood stream within normal limits following oral or intravenous administration of glucose. "The impaired glucose tolerance of the HFD-fed mice was improved by NMN administration, even with somatostatin administration, coincident with an increase in hepatic NAD+ levels." (PMID 29296001, 2018).
intestinal obstruction (1 paper, 2022). Blockage of the normal flow of the intestinal contents within the bowel. "Moreover, due to the early application of analgesics and somatostatin in patients with intestinal obstruction, infection and electrolyte imbalance may occur, which affect intestinal peristalsis." (PMID 36620562, 2022).
Intrauterine growth restriction (1 paper, 2018). "Intrauterine growth restriction in pigs is associated with an increase in brain dopaminergic activity, which leads in consequence to a reduced somatostatin tonus on growth hormone releasing hormone secretion and therefore to higher GH concentrations at least in men." (PMID 29762475, 2018).
ischemic cardiomyopathy (1 paper, 2021). Ischemic cardiomyopathy is a cardiomyopathy in which a weakness in the muscle of the heart due to inadequate oxygen delivery to the myocardium with coronary artery disease being the most common cause. "Cardiac SST showed a decreased expression at the peptide level in the tissue samples of patients with ischemic cardiomyopathy as compared to controls." (PMID 34803662, 2021). "We also measured SST-like immunoreactivity in interventricular septum samples of healthy and ischemic cardiomyopathy patients and demonstrated the first time in the literature that SST is expressed in the human heart tissue at the peptide level." (PMID 34803662, 2021). "Moreover, SST expression was decreased at the peptide level in interventricular septum samples of patients with ischemic cardiomyopathy." (PMID 34803662, 2021).
islet cell carcinoma (1 paper, 2020). "SST mRNA was dramatically increased in QGP over that in NT-3 and BON cells, which is in agreement with the establishment of the QGP cell line from a SST-producing islet cell carcinoma." (PMID 32183367, 2020).
laryngeal carcinoma (1 paper, 2018). Carcinoma that arises from the laryngeal epithelium. "Further analyses showed that the aberrant methylation of SST may be a potential marker for patients with laryngeal cancer that is at low risk of relapse." (PMID 29682090, 2018). "When the SST promoter was methylated in patients with laryngeal cancers, the OR was 0.080 (95% CI 0.018–0.349; P = 0.001)." (PMID 29682090, 2018).
liver cancer (1 paper, 2020). An epithelial or non-epithelial malignant neoplasm that arises from the liver. "To learn whether SST hypermethylation is specific to gastrointestinal tumors, we explored TCGA data of five additional major tumor entities beyond the gastrointestinal tract: lung, breast, prostate, head and neck, as well as liver cancer." (PMID 32243066, 2020).
liver fibrosis (1 paper, 2005). "We have previously shown an association between severe hepatic fibrosis and low levels of endogenous somatostatin." (PMID 15949036, 2005). "Circulating host somatostatin levels might inhibit SEA production via interaction with the SSTR receptors on the parasite surface, thereby regulating the level of liver fibrosis and as a result portal hypertension, variceal bleeding and fatality due to this disease." (PMID 15949036, 2005).
magnesium deficiency (1 paper, 2024). A nutritional condition produced by a deficiency of magnesium in the diet, characterized by anorexia, nausea, vomiting, lethargy, and weakness. "It inhibits somatostatin, which suppresses TSH secretion; it can cause zinc and selenium deficiencies, disrupting thyroid hormone synthesis; and it can lead to magnesium deficiency, which reduces iodine uptake and T4 synthesis, resulting in increased TSH secretion." (PMID 39699485, 2024).
mental disorder (1 paper, 2021). A disease that has its basis in the disruption of mental process. "Our data was in disagreement with previous findings, in which they showed that dysfunction of SST interneurons is likely associated with the pathophysiology of many mental disorders." (PMID 33619236, 2021).
microcephaly (1 paper, 2020). A congenital or acquired developmental disorder in which the circumference of the head is smaller than normal for the person's age and sex. "Rbm8a cKO in neural stem cells results in early postnatal lethality, microcephaly, and leads to decreased number of PV+ and NPY+ cortical interneurons, abnormal distribution of PV+, SST+, and NPY+ interneurons in the cortex, and aberrant GABA transmission." (PMID 33154347, 2020).
Migraine (1 paper, 2022). "Here, we provide insights into these mechanisms by investigating the cortical feedback inhibition microcircuit involving somatostatin-expressing interneurons (SOM INs) in a mouse model of a rare monogenic migraine." (PMID 35863891, 2022).
myocardial ischemia (1 paper, 2021). A disorder of cardiac function caused by insufficient blood flow to the muscle tissue of the heart. "Little is known about the role of the neuropeptide somatostatin (SST) in myocardial ischemia/reperfusion injury and cardioprotection." (PMID 34803662, 2021).
Neoplasm of the endocrine system (1 paper, 2021). A tumor (abnormal growth of tissue) of the endocrine system. "In general, neoplasms of the endocrine system are considered chemoresistant and there are no available efficient anti-cancer treatment options (except in cases when somatostatin analogues can be administered)." (PMID 34257605, 2021).
neurofibromatosis type 1 (1 paper, 2013). A clinically heterogeneous, neurocutaneous genetic disorder characterized by cafe-au-lait spots, iris Lisch nodules, axillary and inguinal freckling, and multiple neurofibromas. "About 43% of somatostatin-producing NETs and 14% of non-MEN1-associated somatostatin-producing NETs are associated with neurofibromatosis type 1." (PMID 23346552, 2013).
oligodendroglioma (1 paper, 2018). A well-differentiated (WHO grade II), diffusely infiltrating neuroglial tumor, typically located in the cerebral hemispheres. "Our results suggest the identification of the specific oligodendroglioma subgroup as a possible target of therapies using SST analogs." (PMID 30193580, 2018).